CANX (calnexin)
Diseases named in the same sentence as CANX in open-access papers (continued):
Sharing a sentence is not in itself a finding about the gene and the disease.
pneumonia (1 paper, 2021). An acute, acute and chronic, or chronic inflammation focally or diffusely affecting the lung parenchyma, caused by an infection in one or both of the lungs (by bacteria, viruses, fungi, or mycoplasma.). "Full length Bl-Eng2 used as an adjuvant in combination with the antigen calnexin, triggered cytokine production by antigen presenting cells, T cell differentiation of corresponding TCR-transgenic 1807 cells and protected mice against pneumonia in a model of lethal pulmonary fungal infection." (PMID 33735218, 2021).
psoriasis (1 paper, 2025). An autoimmune condition characterized by red, well-delineated plaques with silvery scales that are usually on the extensor surfaces and scalp. "HSP90B1 and CANX were significantly increased in psoriasis as clinical control compared with the normal control." (PMID 39938773, 2025).
retinal degeneration (1 paper, 2025). Degeneration of the retina. "Moreover, TMX4 has been shown to interact with calnexin, a protein whose impairment leads to retinal degeneration." (PMID 40429992, 2025).
steatosis (1 paper, 2019). Increased lipid within the cytoplasm of cells. "Histopathological analysis upon termination of the study showed that 50% of the animals exhibited steatosis, occasionally associated with portal inflammation of variable degrees that was correlated with the baseline levels of calnexin in the fibroblasts (P=0.045)." (PMID 30733237, 2019).
tumor (47 papers, 2010 to 2026). "While many of the proteins are reported to be implicated in cancer, calnexin, an ER chaperone protein, is significantly upregulated in several tumor phenotypes and thus used as a sero-diagnostic marker for several cancers." (PMID 36831567, 2023). "Preliminary results with calnexin knockdown indicated that this relationship is not direct or causal and is probably accentuated in an in vivo tumor with heterogenous microenvironmental stresses." (PMID 26334999, 2015). "We believe that HCAb2 is an ideal antibody to target metastatic tumor cells since HCAb2 binds to cell surface HSP90 as well as to cells that are deficient in calnexin." (PMID 26334999, 2015). "It is unclear as to the significance or the cause of reduced levels of calnexin in these tumor cells." (PMID 26334999, 2015). "This suggests that the loss of calnexin in xenograft tumor cells occurred during tumor formation and/or within the tumor microenvironment." (PMID 26334999, 2015). "EdU staining confirmed that the MAPK pathway is crucial for CANX-mediated regulation of tumor proliferation." (PMID 39990231, 2025). "We constructed an orthotopic tumor model in nude mice to further elucidate the role of CANX in GBM development." (PMID 39990231, 2025). "KEGG enrichment analysis suggested that CANX was highly enriched in multiple pathways related to tumor growth, such as ER protein synthesis, cancer pathways, and ECM-receptor interaction mechanisms." (PMID 39990231, 2025). "In tumor cells, E and N calnexin significantly regulate the invasion and metastasis of tumor cells and are two essential factor proteins that influence cell signaling and cell physical connectivity." (PMID 35251569, 2022). "The heterogeneous expression of CD99, HRNR, and CANX in both healthy and tumor tissue hampered the quantitative comparison." (PMID 35267445, 2022). "In mRNA and miRNA sequencing data from the same patient-derived tumor, miR-320a was down-regulated, while CANX expression increased." (PMID 34914716, 2021). "CANX expression is significantly correlated with the transition from the angiogenesis-independent to angiogenesis-dependent (i.e., more invasive) tumor growth." (PMID 32793473, 2020). "The tumour/normal ratios of calnexin (p = 0.0055) were significantly increased in samples from patients who had poor clinical outcome." (PMID 27369741, 2016). "Using quantitative Western blotting, the expression levels of calnexin in tumour biopsy tissue were determined in all 11 patients." (PMID 27369741, 2016). "The tumour/normal ratios of calnexin (p = 0.0093) were significantly increased in samples from patients who received chemotherapy and had poor clinical outcome." (PMID 27369741, 2016). "Cell viability was assessed after 3-MA treatment and BECN1 knockdown using the CCK-8 assay to determine whether CANX-induced autophagy protects tumor cells." (PMID 39990231, 2025). "Both EVs from tumour tissues contain EV proteins, including Flotillin-1 as well as Calnexin." (PMID 31497264, 2019). "However, we observed little variation in the subcellular localization of calnexin in good and poor responders, with cytoplasmic, punctuate calnexin staining in all tumor cells." (PMID 27369741, 2016). "Our data demonstrate that an increased tumour/normal ratio of calnexin, but not calreticulin, was significantly associated with poor clinical outcome in patients that received chemotherapy." (PMID 27369741, 2016). "Increased tumour protein levels of calnexin may be of prognostic significance in CRC, and calnexin may represent a potential target for future therapies." (PMID 27369741, 2016). "Next, to test if the distribution of AGR2 could modify other components of the secretory pathway, a ratiometric comparison of both BiP and CANX was performed in tumor organoids (Sh-ctl) as compared to tumor organoids silenced for AGR2 (Sh-AGR2)." (PMID 27240165, 2016).
tumor (continued). "Our results demonstrated that CANX knockdown effectively inhibited the proliferation of GBM cells and induced tumor apoptosis." (PMID 39990231, 2025). "Aberrant expression of CANX prevents successful assembly of MHC-I, processing of antigenic peptides and presentation on the surface of tumor cells, thus potentially leading to evasion of immune surveillance." (PMID 38230215, 2024). "Significant ilQTLs, the majority of which of somatic origin, were identified in immune-relevant genes, including B2M, HLA genes, CANX, LDHA, PSMB2, and HNRNPR, which are known to affect the tumor immune landscape." (PMID 38773080, 2024). "To investigate the functional role of the CANX/CALR cycle in ITGA5/B1-mediated adhesion to FN, we used MIA PaCa-2 cells expressing an actin-chromobody tagged with GFP to analyze the spreading of tumor cells on FN-coated plates by live-cell imaging." (PMID 37563605, 2023). "In order to study the molecular mechanism of CALR involved in tumor progression, we used String and GeneMANIA databases finding that PDIA3, B2M, GANAB, CANX, and TAPBP interact with CALR." (PMID 34910788, 2021). "The detection of just a partial colocalization with calnexin and Rab11A seems to suggest anyway that HA is mainly localized in the cytoplasm of the MPM tumor cells." (PMID 33499323, 2021). "We found that the expression levels of CANX, BIRC5, BID, and NAMPT in tumor tissues were significantly higher than their expression levels in normal tissues, indicating that they are all significantly related to tumor occurrence and development." (PMID 34988121, 2021). "Through a screening in TCGA-KIRC database, we compared the expression levels of CANX, MAPK1, BIRC5, NAMPT, and BID in normal kidney tissues and renal clear cell tumor tissues, and we found that their expression levels in tumor tissues were upregulated." (PMID 34988121, 2021). "Patient samples were subdivided by disease stage, stage II and stage III, and the ratio of calreticulin, calnexin, GRP78 and GRP94 in tumour versus normal tissue was evaluated." (PMID 27369741, 2016). "Calnexin (CANX) complexes on the cell surface can reduce the number of extracellular disulfide bonds, thereby degrading the extracellular matrix, which serves as a physical barrier to HCC growth, thereby inducing tumor growth and invasion." (PMID 40051627, 2025). "In a previous study, CANX was found to promote T cell activation and IFN-γ and TNF-α secretion by positively regulating MHC-1, thus enhancing the T cell killing effect on mouse tumor cells and immunocyte infiltration." (PMID 40787468, 2025). "Moreover, we checked the expression of contamination markers albumin, calnexin and Gm130 as well as another EV marker TSG101 in both EVs and tumor tissues by Western Blot as a quality control of EV isolation." (PMID 33391510, 2021). "BID, NAMPT, and BIRC5 were detected with the same results in tumor tissues and with adjacent normal kidney tissues, while CANX was not significantly different." (PMID 34988121, 2021). "In addition, the response of CANX, BID, NAMPT, and BIRC5 with different expression levels to immune checkpoint inhibitors was predicted based on Tumor Immune Dysfunction and Exclusion (TIDE) algorithm." (PMID 34988121, 2021). "Remarkably, ER-localization of GALNTs in the GALA pathway induces O-Glycosylation of the matrix metalloprotease MMP14 and ER-resident Calnexin, thus drives MMP14 activation and Calnexin/ERp57 cell surface distribution, respectively, both of which promote ECM degradation and tumor development." (PMID 34055798, 2021). "The effective isolation of EVs was confirmed by western blot analysis, with positive signal for the tetraspanins CD9, CD63, CD81 and Tumour Susceptibility Gene 101 (TSG101), while negative for the cellular marker calnexin." (PMID 33216826, 2020).
tumor (continued). "We likewise found elevated protein levels of calnexin in tumour (p = 0.0030) but not matched normal tissue of patients with poor outcome when comparing tumour and matched normal samples independently." (PMID 27369741, 2016). "The antigen for HCAb2 was found to be HSP90 and HCAb2 bound to a unique subset of xenograft tumor cells that were negative for calnexin." (PMID 26334999, 2015). "The HE staining results confirmed the difference in tumor growth among the groups, while staining of CANX, MAP1LC3B, MKI67, and cleaved Caspase 3 confirmed that ND could enhance chemotherapy sensitivity in vivo by reducing the expression of CANX." (PMID 39990231, 2025). "Immunohistochemical analysis of CD99, HRNR, and CANX confirmed the expression of these markers in the prostate but, due to high heterogeneity, with high- and low-expression areas in both healthy and tumor tissues, it was not possible to compare the two conditions." (PMID 35267445, 2022). "In each tumor cell line, exposure to radiation significantly increased the expression of ≥ 6 APM components by ≥ 30%, namely the immunoproteosome subunits LMP2, LMP7, and LMP10; the peptide transporters TAP1 and TAP2; and the chaperones calnexin (2/3 cell lines) and tapasin (3/3 cell lines)." (PMID 24480782, 2014). "Finally, HCAb2 specifically targeted calnexin negative xenograft tumor cells." (PMID 26334999, 2015). "TEX harvested from tumor cell supernatants by SEC had vesicular morphology, were sized at 50–200 nm (median = 105 nm), and carried CD9, TSG101, and ALIX but were negative for calnexin." (PMID 40121518, 2025).
infection (46 papers, 2008 to 2026). The state of being infected such as from the introduction of a foreign agent such as serum, vaccine, antigenic substance or organism. "Despite observing Golgi fragmentation by immunofluorescence during RV-C15 infection as previously reported for other RVs, a high ratio of calnexin-dsRNA colocalization implicated the endoplasmic reticulum as the primary site for RV-C15 replication in HAE." (PMID 34995322, 2022). "Indeed, when examining the co-localization scores over time, we found that FABP4’s association with dsRNA and calnexin occurred as early as 8 h post infection, and peaked at 12 to 24 h." (PMID 39843629, 2025). "At 48 h post-infection, untreated wild-type BCVs showed low colocalization with LAMP-1, high colocalization with the ER marker calnexin, and minimal association with p62, consistent with maturation into ER-derived replicative BCVs." (PMID 41542404, 2026). "Quantification of the total area and size of distinct clusters of ER marker (calnexin) signal between mock and HAstV1 infected cells revealed that infection resulted in significant ER membrane condensation and network fragmentation, respectively." (PMID 40982531, 2025). "The co-localization between calnexin and dsRNA on the other hand was at its peak 48 h post infection." (PMID 39843629, 2025). "Consistent with the transcript data, we observed an increase in the level of Calnexin upon infection with STM WT at 16 h post-infection compared with STMΔssaV." (PMID 40272166, 2025). "Corresponding 1807 TCR transgenic (calnexin-specific) T cells expanded not only after infection with B. dermatitidis but also after challenge with other dimorphic fungi including C. posadasii and H. capsulatum." (PMID 41061037, 2025). "We then evaluated the multiplication of bacteria within their replicative compartment at 48 h post-infection by colocalization with the ER-marker calnexin." (PMID 37234533, 2023). "We separated the cytosolic fraction from the membrane fraction (validated by probing for alpha-tubulin, and calnexin respectively) and Cbp1 localized exclusively to the cytosolic fraction, suggesting it exits the Hc-containing phagosome during infection." (PMID 35731824, 2022). "This distribution was confirmed by the strong colocalization of ApoE, Zika E protein and calnexin, a marker of the ER compartment, 24 h post-infection." (PMID 35902969, 2022). "As reported for the ER proteins calnexin and glucose 6-phosphatase, the number of Sec61β-positive LCVs increased over the course of infection, and around 70% of the LCVs was detected as Sec61β-positive vacuoles at 6 h post infection." (PMID 33760868, 2021). "Later on, LAMP-2+ BCVs progressively decreased and at 24 h after infection the majority of bacteria were enclosed within calnexin+ (endoplasmic reticulum marker) vacuoles and they remained positive for calnexin up to 48 h post-infection." (PMID 29963502, 2018). "After 24 h of infection, the majority of bacteria were enclosed within calnexin positive vacuoles (ER marker) and remained there even after 48 h of infection." (PMID 29963502, 2018). "To determine the localization of UGGT1 in cells following EVA71 infection, we used an anti-calnexin (CNX) antibody to evaluate proteins located in the ER in an immunoprecipitation assay." (PMID 28545059, 2017). "ER chaperones calnexin and calreticulin are markedly increased 16 hours post-infection (hpi) and protein disulfide isomerase (PDI) at later infection time points (48 hpi)." (PMID 28841179, 2017). "Conversely, infection by ΔdotA mutant L. pneumophila, which lack a functional Dot/Icm secretion system, resulted in minimal levels of anti-Calnexin staining (~2%) and substantial anti-LAMP1 colocalization (~74%)." (PMID 27459495, 2016).
infection (continued). "Consistent with previous studies, approximately 85% of LCVs isolated in a post-nuclear supernatant at 1 h post-infection stained positive for the ER protein Calnexin, indicating successful recruitment of membrane traffic from the host secretory pathway." (PMID 27459495, 2016). "In support of this interpretation, we observed a similar localization pattern of the ER marker calnexin at this time point of infection." (PMID 25822891, 2015). "Upon infection of D. discoideum producing the ER/LCV marker calnexin-GFP with red fluorescent L. pneumophila producing M45-tagged LegG1, the effector protein accumulated in an Icm/Dot-dependent manner on the LCV membrane." (PMID 24068924, 2013). "We have demonstrated that infection efficiency can be significantly affected by ablating proteins involved in sorting or degradation: calnexin, KDEL-R, β-COP, or PSMB3." (PMID 21625534, 2011). "We further quantified the levels of ER-resident proteins Calnexin and BiP during infection." (PMID 40272166, 2025). "Both endogenous and mRFP-tagged Rab6A and Rab33B were detected in a significant fraction of LCVs, and the recruitment of these Rabs to the LCVs are increasing at 2 h post infection, corresponding to the time when ER protein calnexin starts to accumulate on the LCV." (PMID 33760868, 2021). "Similarly, upon infection of calnexin-GFP-producing D. discoideum with L. pneumophila strain Paris or the ΔpieG mutant, LCV motility was reduced by approximately 25%." (PMID 32209684, 2020). "Similarly, the 13-mer peptide (LVVKNPAAHHAIS), which was generated from the conserved region amino acid determinant within chaperone calnexin, stimulated protective immune responses, and vaccination reduced the severity of infection with B. dermatitidis." (PMID 32722452, 2020). "UL148 was previously observed to colocalize with the ER marker calnexin during infection." (PMID 31822584, 2019). "Infection with dimorphic or opportunistic fungi induces calnexin-specific CD4+ T cells." (PMID 28344577, 2017). "At day 4 post-infection, mice vaccinated with calnexin+Bl-Eng-2 and calnexin+Alum+Bl-Eng-2 showed increased activation and killing by neutrophils and alveolar macrophages vs. calnexin and calnexin+ Alum controls." (PMID 28793349, 2017). "Furthermore, infection with other clinically relevant ascomycetes such as Aspergillus fumigatus, Fonsecaea pedrosoi, and Pseudogymnoascus destructans triggered the expansion of calnexin peptide–MHC II tetramers." (PMID 41061037, 2025). "Moreover, because of the ability of calnexin to induce the clonal expansion of calnexin-specific CD4+ T cells during infection, this vaccine may present an immunotherapeutic effect." (PMID 37367569, 2023). "Throughout the infection (2-20 h p.i.), the treatment of the parental D. discoideum strain with LAI-1 resulted in a significantly smaller size of calnexin-GFP-positive LCVs and P4C-positive LCVs." (PMID 40300029, 2025). "We further validated our findings on a real infection model, and found that ALSV infection induced calnexin transferring into the nucleus of HepG2 cells using the immunofluorescence and cell fractionation analysis." (PMID 36238596, 2022). "The expression of PERK, Calnexin, Ero1-Lα and BIP in Ad-Vp3-infected cells were significantly higher at 12 and 24 h, and significantly lower at 36, 48, and 72 h post-infection when compared with the Ad-Mock infected cells (p < 0.05)." (PMID 33718168, 2021). "In this study, we found that the expression of the ER stress related proteins PERK, Calnexin, Ero1-l α, BIP, and PDI was significantly higher in the Ad-Vp3-infected HepG-2 cells compared to Ad-Mock-infected HepG-2 cells, 12 h and 24 h post-infection." (PMID 33718168, 2021). "Post infection, NS1 and NS3 of DV and human PTB are observed to co-localize with the endoplasmic reticulum marker calnexin." (PMID 34583643, 2021). "The majority of genes (CANX, B2M, CD74 and CTSB) in Antigen processing and presentation pathway were downregulated during infection." (PMID 33177569, 2020).